FAM138F (family with sequence similarity 138 member F)
Synonyms: F379
Gene: Long non-coding RNA gene on chromosome 19 (76,162 to 79,204, reverse strand). Ensembl gene ENSG00000282591.
Homologues: Paralogues in human: FAM138A (100% identical).